H19 (H19 imprinted maternally expressed transcript)
Diseases named in the same sentence as H19 in open-access papers (continued):
Sharing a sentence is not in itself a finding about the gene and the disease.
breast cancer (continued). "To further investigate the involvement of lncRNA H19 and miR-675 in breast cancer cell aggressiveness, we then investigated if lncRNA H19 and miR-675 could endow the cells with stemness properties." (PMID 32610610, 2020). "Besides, H19, an oestrogen‐inducible lncRNA, was reported to function in the cell survival and proliferation, which was from the oestrogen in breast cancer cells." (PMID 32530560, 2020). "We identified the long noncoding RNA H19 as a potential marker for breast cancer in Lebanese women." (PMID 33335214, 2020). "Quantitative real-time PCR analyzed expression of H19 in tamoxifen-resistant breast cancer tissues." (PMID 31340867, 2019). "LncRNA H19 (H19), the product of H19 gene, is maternally expressed and paternally imprinted, and has been described as an oncogene in various cancers, including bladder, colorectal, gastric and breast cancers." (PMID 31170091, 2019). "Regulations of Let‐7/LIN28 axis by altering H19 controlled the fate of CSCs of triple negative breast cancer, but how H19 functioned in CSCs from Lumina A/B breast cancer was unknown." (PMID 30338598, 2019). "Further research and technical innovation regarding the inhibition of H19 could provide opportunities for H19-targeted therapies in tamoxifen-resistant breast cancer." (PMID 31340867, 2019). "H19 also affects drug resistance in breast cancer via the H19-CUL4A-ABCB1/MDR1 pathway." (PMID 31777598, 2019). "Here, we assessed the role of H19 in the development of tamoxifen-resistant breast cancer." (PMID 31340867, 2019). "However, H19 was also suggested as a biomarker for breast cancer and gastric cancer after discovering increased H19 levels in plasma in these patients." (PMID 30893946, 2019). "Furthermore, H19 supports sphere formation in breast cancer cells, as well as transporter expression and anti-cancer-drug resistance in hepatocellular carcinoma cells." (PMID 30410672, 2018). "Moreover, H19 can act as a ceRNA to sponge let-7 and upregulates Lin28 expression in breast cancer cells; in turn, this induction of Lin28 expression further restricts let-7 function." (PMID 30134946, 2018). "Recent evidence indicates that H19 enhances invasion and metastasis in bladder cancer, glioma, osteosarcoma, acute myeloid leukemia, breast cancer, non-small cell lung cancer, gastric cancer, and pancreatic cancer, but suppresses the aggressiveness of hepatocellular carcinoma and prostate cancer." (PMID 30410672, 2018). "Moreover, when breast cancer cells were cultured under hypoxic conditions (O2=1%) to mimic the xenograft tumor central microenvironments, H19 expression levels were the highest amongst all lncRNAs studied in both MDA-MB-231 cells and MCF-7 cells under hypoxia." (PMID 29106390, 2018). "Besides its role in breast cancer, CSRP2 was recently identified as a downstream target of H19, the long non-coding RNA with the strongest association with colorectal cancer patient survival." (PMID 29976963, 2018). "We found that H19 and miR-675 expression enhances breast cancer cell migration." (PMID 29099749, 2017). "Using Dox-resistant MCF-7 breast cancer cells developed by incremental increases in Dox concentrations, we observed in the current study that H19 expression was greatly upregulated in Dox-resistant cells as well as in parental MCF-7 cells treated with anthracyclines." (PMID 29190892, 2017). "Particularly, H19 lncRNA is overexpressed in approximately 70% of breast cancers." (PMID 29190892, 2017). "However, the functional significance and mechanism of H19 lncRNA in breast cancer chemoresistance is poorly understood despite its significant role in cancer development and progression." (PMID 29190892, 2017). "In this review, we summarize the different mechanisms of action of H19 in human breast cancer." (PMID 29099749, 2017).
breast cancer (continued). "Moreover, we found that CUL4A, an ubiquitin ligase component, was a critical factor bridging H19 lncRNA to MDR1 expression, and a high tumor CUL4A expression was associated with low survival in breast cancer patients treated with chemotherapy." (PMID 29190892, 2017). "As LIN28 was a validated target of let-7, we examined whether LIN28 was regulated by the H19/let-7 axis in breast cancer cells." (PMID 28102845, 2017). "In addition, the Kaplan–Meier survival analysis demonstrated that high H19 level was a strong indicator for an inferior overall survival in breast cancer patient samples." (PMID 28102845, 2017). "Moreover, overexpressing H19 in another breast cancer cell line SK-BR-3, also resulted in similar increases in self-renewal properties." (PMID 28102845, 2017). "In addition, analysis of a dataset in GEO (GSE52544) with CUL4A depletion in breast cancer cells indicated that 7 molecular pathways affected by CUL4A knockdown were converged to those with H19 knockdown." (PMID 29190892, 2017). "The impact of H19 on metastasis abilities of the human breast cancer cell could be due to the sponging of these microRNAs." (PMID 29099749, 2017). "In this review, we will focus on the role of H19 in human breast cancer." (PMID 29099749, 2017). "Aberrant H19 expression in breast cancer could arise through various mechanisms, including chromosomal abnormalities, transcription factor binding, and epigenetic alterations." (PMID 27845892, 2016). "In recently reports, H19 exerted two opposite effects depending on tumor types: it functioned as an oncogene in ovarian cancer, colorectal cancer, breast cancer and glioblastoma; whereas, it exerted tumor suppression effects in hepatocellular carcinoma, prostate cancer and Wilms’ tumor." (PMID 27716361, 2016). "For example, H19 is an estrogen-inducible gene and plays a key role in cell survival, which may serve as a biomarker for breast cancer diagnosis and progression, and a significantly decreased risk of bladder cancer was found for H19 rs2839698 TC carriers." (PMID 26967566, 2016). "H19 is also a precursor for miR-675 that enhances the aggressive phenotype of breast cancer cells." (PMID 27626436, 2016). "Elevated expression of H19 was only observed in ERα-positive PTX-resistant breast cancer cell lines (MCF-7 and ZR-75-1) in our study; therefore, we proposed that ERα could activate H19 expression." (PMID 27845892, 2016). "Previous studies have shown that H19 was an oncogene in breast cancer." (PMID 27897214, 2016). "Our findings in the present study indicate that high expression of lncRNA H19 may reduce the sensitivity of breast cancer cells to chemotherapy through inactivation of pro-apoptosis pathways." (PMID 27845892, 2016). "Altered ERα expression may therefore change H19 levels to modulate the apoptosis response to chemotherapy in breast cancer cells." (PMID 27845892, 2016). "The overexpression of lnc-MTAP (CDKN2B-AS1), lnc-PCP4 (DSCAM-S1), and lnc-FAM (H19) in breast cells suggests that these lncRNAs may have significant role to play in breast cancer." (PMID 30159409, 2016). "Additionally, they identified the ubiquitin ligase E3 family (c-CbI and CbI-b) as direct targets of miR-675 in breast cancer cells, providing novel mechanistic insights into a role of lncRNA H19 in breast cancer development." (PMID 27608009, 2016). "Altogether, these results strongly support the idea that HMGA1P7 could act as ceRNAs in human breast cancer and represent a novel potential mechanism accounting for H19 and IGF2 upregulation in these tumors." (PMID 27874091, 2016). "H19 was overexpressed in many types of cancer including bladder, pancreatic and breast cancer." (PMID 27613832, 2016). "We previously confirmed that H19 inhibits transcription of BIK and NOXA in breast cancer, however, the underlying mechanism is still unknown." (PMID 27845892, 2016). "This is the first confirmation of a role for H19 in breast cancer drug resistance." (PMID 27845892, 2016).
breast cancer (continued). "We also confirmed that H19 bound to EZH2 in breast cancer cells." (PMID 27845892, 2016). "In the present study, the high expression of lncRNA H19 was identified as a powerful factor associated with paclitaxel (PTX) resistance in ERα-positive breast cancer cells, but not in ERα-negative breast cancer cells." (PMID 27845892, 2016). "Our findings provide novel mechanistic insights into a critical role for H19 RNA in breast cancer development and reveal a previously unknown link between H19/miR-675, Cbl and tyrosine kinase receptors to enhance breast cancer cell aggressiveness." (PMID 26353930, 2015). "We have previously shown that H19 is overexpressed in 70% of breast cancer." (PMID 26353930, 2015). "Indeed, silencing of H19 in breast cancer cells reduces their proliferation while H19 overexpression accelerates cell cycle progression." (PMID 26536864, 2015). "Our data describe a novel mechanism of protumoral action of H19 in breast cancer." (PMID 26353930, 2015). "In the present report, we provide evidence that ligand-activated ERα binds to six ERE sites within the H19 promoter and could directly activate the transcription of this gene in breast cancer cells." (PMID 25944846, 2015). "In addition to autocrine factors (hepatocyte growth factor or fibroblast growth factor 2), H19 expression is also regulated by estrogen signaling in ERα+ breast cancer cells." (PMID 25944846, 2015). "Altogether theses finding are in favor of a role of H19 as an oncogene in breast cancer." (PMID 26353930, 2015). "Together, these data indicate that c-Cbl and Cbl-b may be negatively regulated by H19 in breast cancer cells." (PMID 26353930, 2015). "Moreover, it was experimentally shown in breast cancer cells that Rb indirectly suppresses H19 expression by repressing E2F1, while in colorectal cancer cells and in hepatocellular carcinoma cells, H19 derived miR-675 negatively regulates Rb expression." (PMID 26536864, 2015). "However, some research shows that H19 expression and DNA methylation are often abnormal in human bladder carcinoma, human testicular germ cell tumors, and breast cancer." (PMID 24015185, 2013). "This suggests that H19 may act as a predictive biomarker for aggressive breast cancer morphologies." (PMID 39997609, 2025). "Therefore, targeting the H19/ILF2/BRCA1 axis might modulate therapeutic approaches in breast cancer." (PMID 37298108, 2023). "Hence, it is apparent that H19 reduces sensitivity to PARP inhibition in breast cancer cells." (PMID 37298108, 2023). "In addition, metformin may promote ferroptosis by blocking autophagy through the small interfering RNA, H19, potentially making it easier to design innovative medicines for breast cancer." (PMID 36766800, 2023). "Likewise, up-regulation of lncRNA HOTAIR and MALAT1, down-regulation of lncRNA Meg3 and dual function of lnRNA H19 were seen in different cancer types, including lung cancer, ovarian cancer, prostate cancer, breast cancer, colorectal cancer, gastric cancer, and liver cancer." (PMID 37568568, 2023). "Consequently, in this review, we analyze the impact of lncRNA H19 as a responsible factor in chemo and radioresistance of malignant cells, including their underpinning molecular mechanisms, specifically breast cancer, lung adenocarcinoma, glioma, and colorectal carcinoma." (PMID 35955440, 2022). "However, the overexpression of H19 can contribute to the chemoresistance of breast cancer cells." (PMID 35415316, 2022). "Thus, the overall results indicated that serum exosomal H19 could be a novel biomarker for breast cancer diagnosis." (PMID 35172817, 2022).
breast cancer (continued). "Mechanistically, H19 promotes expression of Cullin 4A (CUL4A), a ubiquitin ligase component, which in turn enhances expression of ABCB1/4 genes that encoded MDR1/4 proteins, two members of the ATP-binding cassette family highly upregulated in several carcinomas, including breast cancer." (PMID 35955440, 2022). "H19 could regulate breast cancer cell processes by acting on the Wnt/β-catenin signaling pathway." (PMID 34977037, 2021). "Additionally, downregulation of H19 expression could result in S-phase arrest of breast cancer cells, suggesting its role in regulating cell cycle progression." (PMID 34527584, 2021). "Moreover, lncRNA H19 may promote breast cancer tamoxifen resistance through modulation of the SAHH/DNMT3B axis." (PMID 34026654, 2021). "Study found that lncRNA H19 (H19) may play a mediating role between c-Myc and downstream gene expressions in colon cancer, and is up-regulated in liver cancer, bladder cancer and breast cancer, suggesting that H19 may be related to the occurrence of cancer." (PMID 33403385, 2021). "Besides, H19 acts as a ceRNA for Let-7 to maintain the activation of breast cancer stem cells." (PMID 33330574, 2020). "The expression pattern of H19 in TN breast cancers may be different from ER-positive breast cancer." (PMID 32190687, 2020). "However, whether H19 takes part in the dysregulation of PARP1 expression in breast cancer cells remains unknown." (PMID 32345117, 2020). "Moreover, microarray data identified H19 as a potential target of Huaier (a fungal parasite on locust trees), the extract from which reduced the expression of H19, while also reducing the viability of breast cancer cells by inducing apoptosis via regulation of the H19-miR-675-5p-CBL axis." (PMID 33680956, 2020). "However, H19 is overexpressed in 73% of breast cancer tissues in comparison with healthy ones." (PMID 33335214, 2020). "However, the tumor volume of pCMV6-H19/Dox group was smaller than that of pCMV6/Dox group, and significant difference in the tumor volume was observed between the two group, suggesting that enforced H19 was resistant to Dox breast cancer cells in vivo." (PMID 32345117, 2020). "Knockout of the H19 gene could make breast cancer cells re-sensitized to tamoxifen." (PMID 33362547, 2020). "Thus, exosomal H19 can be a potentially useful biomarker for the diagnosis of breast cancer." (PMID 32924276, 2020). "However, the tumor volume of H19 shRNA/Dox group was smaller than that of NC shRNA/Dox group, and significant difference in the tumor volume was observed between the two group, suggesting that targeting H19 expression sensitizes breast cancer cells to Dox in vivo." (PMID 32345117, 2020). "Moreover, the lncRNA H19 is to facilitate glycolysis and breast cancer stemness under hypoxia." (PMID 29106390, 2018). "Some of these targets could explain the oncogenic role of H19 in breast cancer." (PMID 29099749, 2017). "It suggested PR might also be involved in breast cancer chemoresistance in related to H19." (PMID 27845892, 2016). "Therefore, therapies that target the regulatory signaling axis ERα-H19-BIK may increase the overall effectiveness of breast cancer chemotherapy." (PMID 27845892, 2016). "However, in the present study, knockdown of H19 significantly reversed resistance even to drugs that were not substrates of P-glycoprotein, indicating H19 induced breast cancer chemoresistance through regulation of basic cellular activities rather than by drug efflux." (PMID 27845892, 2016). "Transfection of H19 in breast cancer cells also increases their ability to form tumors when injected into mice and its overexpression leads to an increase in breast cancer proliferation by increasing entry into S phase, whereas knockdown prevented cell cycle progression through S phase." (PMID 25400658, 2014).
breast cancer (continued). "A breast cancer association was seen for six of the 14 tested SNPs; rs2981582 (FGFR2) 1.28 (1.12-1.47), rs3803662 (TNRC9) 1.20 (1.04-1.39), rs12443621 (TNRC9) 1.19 (1.04-1.35), rs889312 (MAP3K1) 1.18 (1.02-1.36), rs3817198 (LSP1) 1.17 (1.10-1.35) and rs2107425 (H19) 0.86 (0.75-0.99)." (PMID 22867275, 2012). "The H19/LincRNA H19/miR-675/MRP3-HOXA1-MMP16 axis offers promising targets for new therapeutic strategies, reflecting the complex interplay between genetic markers and breast cancer pathology." (PMID 39267845, 2024). "The expression levels of LincRNA H19, miR-675, MRP3, HOXA1, and MMP16 in breast cancer tissues also suggest a strong link with the early onset and types of breast cancer, with MRP3 showing high prognostic value." (PMID 39267845, 2024). "Correlations of LincRNA H19, miR-675, MRP3, HOXA1, and MMP16 with clinicopathological parameters in patients with breast cancer." (PMID 39267845, 2024). "For example, the |log2 fold change| of lncRNA LINC00472, H19 and PVT1 are all less than 2, but there are still studies showing that they are related to breast cancer." (PMID 38978021, 2024). "Elevated expression levels of both lncRNA H19 and TNFAIP8 are observed in breast cancer tissues and cell lines, particularly in TNBC." (PMID 39479021, 2024). "It was demonstrated that increased expression of H19 increases DNA DSB repair, which results in reduced sensitivity to PARP inhibition in breast cancer cells." (PMID 37298108, 2023). "In conclusion, this study demonstrated that lncRNA H19 directly binds to ILF2 and thereby co-regulates DNA damage response and sensitivity to PARP inhibitors in breast cancer." (PMID 37298108, 2023). "Currently, several examples of lncRNAs have been described as potential clinical biomarkers for predicting response to therapy or for prognosis in breast cancer, such as HOTAIR, H19, and DSCAM-AS1." (PMID 37108589, 2023). "The main mechanism of LncRNAs is through the competitive binding mechanism of miRNAs, and LncRNA H19/miR-675 and LncRNA NEAT1/miR-204 have been reported to interact in a competitive binding manner in breast cancer." (PMID 37280692, 2023). "In this study, in silico cross-screening of NGS data for lncRNAs associated with DNA damage response and PARP inhibitor resistance was performed, demonstrating that long noncoding RNA H19 regulates both DDR and sensitivity to PARPis in breast cancer." (PMID 37298108, 2023). "In contrast, other circulating lncRNAs (H19, SPRY4‐IT1, XIST, UCA1, AC026904.1, CCAT1, CCAT2, ITGB2‐AS, and AK058003) were significantly up‐regulated in breast cancer patients compared to controls." (PMID 36274054, 2023). "The nuclear and cytoplasmic localization of H19 was determined by use of RNA fluorescence with in situ hybridization (RNA-FISH) in MCF-7 cells and cellular fractionation in T47D and HCC1937 breast cancer cells." (PMID 37298108, 2023). "In breast cancer cells, forced expression of H19 promotes DNA damage repair and resistance to PARP inhibition, whereas H19 depletion diminishes DNA damage repair and increases sensitivity to PARP inhibitors." (PMID 37298108, 2023). "Immunoprecipitation assays provided evidence that lncRNA H19 regulated the expression of STAT3 (Signal transducer and activator of transcription 3) gene in breast cancer." (PMID 36685962, 2022). "In addition, experiments showed that lncRNA H19 expression in the postoperative serum sample was significantly lower than preoperative levels (P|0.000 6), suggesting that H19 could be used for pre-testing in addition to being a breast cancer marker." (PMID 35310927, 2022). "Another study pointed out that exosomal H19 promotes proliferation and invasion of breast cancer using miR-152/DNMT1 axis, providing a new mechanism for breast cancer development." (PMID 36203417, 2022).